IL4 (interleukin 4)
Diseases named in the same sentence as IL4 in open-access papers (continued):
Sharing a sentence is not in itself a finding about the gene and the disease.
breast carcinoma (continued). "An inverted cytokine receptor composed of the IL-4 receptor exodomain fused to the IL-7 receptor endodomain improved the persistence and anti-tumor activity of anti-MUC1 CAR T-cells against an IL-4-secreting breast cancer CDX model." (PMID 38201551, 2023). "There was a substantial increase in IL-24, an IL-4-induced cytokine with demonstrated targeted anti-breast cancer activity." (PMID 38203396, 2023). "The high CCL11 level was shown to increase the proportion of immunosuppressive CD4+CD25+Foxp3+ Tregs in a breast cancer model, indicating the pro-tumoral effect of the IL-4/CCL11 interaction." (PMID 37445941, 2023). "To investigate how 4T1 cells affect M2-like TAMs and the role of FSTL1 during breast cancer metastasis, we treated 4T1 cells with FSTL1/IL4 and detected the expression of some M2-like TAMs-associated factors using q-PCR." (PMID 37238210, 2023). "Breast cancer progression is facilitated by IL4, a pleiotropic cytokine secreted by fibroblasts, Th2, adipose-derived stem cells (ADSCs), as well as breast cancer cells." (PMID 37238871, 2023). "IL-4-activated macrophages co-cultivated with breast cancer cells without direct secreted miR-223-enriched microvesicles promoting the invasion of breast cancer cells via upregulating Mef2c." (PMID 36831498, 2023). "Among anti-inflammatory cytokines, the same trend was noted: the content of IL-4 decreased (−15.1%), and IL-10 increased in breast cancer (+24.5%)." (PMID 36286034, 2022). "In circWWC3 high-expressed breast cancer tissues, the expression of IL-4 and PD-L1 in breast cancer cells was also high, which suggested the possible positive correlation between circWWC3 and IL-4 as well as PD-L1 in breast cancer cells in vivo." (PMID 35996149, 2022). "Here, we demonstrated that IPD indeed increased the ratio of Th1/Th2 cells in breast cancer and suppressed the secretion of IL-4 in both peripheral blood and tumors." (PMID 36564797, 2022). "T cells in the mLN exhibited conversion from a pro-inflammatory state with high IFN-γ expression to an anti-inflammatory state with high expression of IL-4 and IL-10 in early- to late-stages of breast cancer development." (PMID 36232335, 2022). "It was shown that, compared with healthy controls, in the saliva of breast cancer patients, there is an increase in the content of both pro-inflammatory (IL-2, IL-6, and IL-18) and anti-inflammatory cytokines (IL-4 and IL-10)." (PMID 36286034, 2022). "Taken together, our results suggested that circWWC3 upregulates the expression and secretion of IL-4 in breast cancer cells." (PMID 35996149, 2022). "We developed and evaluated the effect of EVs obtained from macrophages polarized with different stimuli, including LPS, IFN-γ, HA, CV, and IL4, in preclinical models of breast cancer." (PMID 35631654, 2022). "According to our data, the level of IL-4 in saliva remains almost constant both against the background of fibroadenomas and in breast cancer." (PMID 36286034, 2022). "In contrast, overexpression of circWWC3 increased the expression and secretion of IL-4 in breast cancer MDA-MB-453 cells which has low expression of circWWC3." (PMID 35996149, 2022). "By contrast, in circWWC3 low-expressed breast cancer tissues, the expression of IL-4 and PD-L1 was low, and M2-type macrophages in breast cancer microenvironment were relatively decreased." (PMID 35996149, 2022). "Co-implantation of CSF-1/IL-4-generated M2 macrophages greatly enhanced tumor lymphatic formation and metastasis in lung and breast carcinoma mouse models, while depletion of M2-TAMs significantly inhibited both processes." (PMID 35442077, 2022). "Although the effects of IL-4 and IL-10 in breast cancer development are inconclusive toward anti- and pro-tumor effects, late-stage breast cancer patients exhibited high levels of these cytokines in their sera." (PMID 36232335, 2022).
breast carcinoma (continued). "In the current study, using models of breast cancer metastasis to the lung, we indicate that IL4 regulates aspects of the differentiation of monocytes to MAMs." (PMID 36077870, 2022). "Taken together, our results indicated that circWWC3 promotes breast cancer progression through facilitating M2-like TAM polarization and PD-L1 expression of TAMs as well as breast cancer cells via regulating IL-4 expression in vivo." (PMID 35996149, 2022). "It has been shown that IL-4, via IL-4Rα, stimulates glutamine metabolism to support cell growth in breast cancer cells." (PMID 34769439, 2021). "This network of proinflammatory components competes with inhibitory effect of anti-inflammatory cytokines (IL-4) on breast cancer cells growth and promotes cell proliferation, tumorigenesis and metastasis." (PMID 35111484, 2021). "In 4 T1 breast cancer cells, IL4Rα enhanced tumor growth by mediating IL4-related enhancement of glucose and glutamine metabolism." (PMID 33419470, 2021). "In breast cancer cells, IL-4 exerts a wide spectrum of pro-tumorigenic effects by reducing expression of dual specificity phosphatase 4 (DUSP4), which negatively regulates ERK and p38 activity." (PMID 34769439, 2021). "For example, IL-4 was considered to be closely related to the poor outcome of breast cancer according to the correlation between hormone receptor negativity and an increase in IL-4 in patients who died from breast cancer." (PMID 33804263, 2021). "Activation of IL4/IL13 signaling pathways increases breast cancer invasion and propensity for lung metastasis." (PMID 34571811, 2021). "Mechanistically, overexpression of linc00514 stimulated IL-6 and IL-4 secretion of breast cancer cells via STAT3/Jagged1 axis, and promoted monocyte polarization into M2-like macrophages and increase the tumor progression." (PMID 32943090, 2020). "Subsequently, Jagged1-mediated Notch signaling pathway promoted IL-4 and IL-6 secretions in breast cancer cells and ultimately inducing M2 polarization of macrophages." (PMID 32943090, 2020). "IL-4 induces the protease activity of cathepsins that promotes breast cancer invasion and metastasis; other factors secreted by TAMs, such as TGF-β, VEGF, CCL8, COX-2, SPARC, MMP9, and MMP2 contribute to the metastatic properties of cancer cells." (PMID 33050070, 2020). "Our analysis of mRNA expression data sets revealed a positive correlation between survival and coexpression of IL-31Ra, IL-2 and IL-4 in breast cancer biopsies." (PMID 32843492, 2020). "IL-4 (Interleukin 4)-activated TAMs release exosomal miR-223, which favored invasion and aggressiveness in breast cancer cells by the activation of the Mef2c-βcatenin pathway (Myocyte enhancer factor 2c-βcatenin)." (PMID 31952362, 2020). "Meanwhile, we found that the siRNA-mediated JAG1 knockdown impairs the secretion and expression of IL-4 and IL-6 of breast cancer cells." (PMID 32943090, 2020). "We therefore investigated the role of MYC in bone marrow macrophages (BMM), polarized towards an M2 phenotype with IL-4 or with media conditioned by a breast cancer cell line." (PMID 32685002, 2020). "We believed that the induction of M2 polarization of macrophages is related to the activation of Jagged1-mediated Notch signaling pathway and the increased secretions of IL-4 and IL-6 in breast cancer cells." (PMID 32943090, 2020). "Our data show that IL-4/IL-13 in vitro differentiated M2a macrophages significantly increase migratory and invasive potential of breast cancer cells at a greater rate than M2b or M2c macrophages." (PMID 31214501, 2019). "The conditioned medium from M2 macrophages after IL-4/IL-13 induction (M2CM) significantly improved the migration ability of breast cancer 4T1 cells in vitro." (PMID 30766614, 2019). "Conversely, IL4 inhibited proliferation of human renal, colon, and breast cancer cells in addition to inducing regression in mouse xenograft models of renal cancer." (PMID 31779626, 2019).
breast carcinoma (continued). "The Th2 subset produces the classical anti-inflammatory cytokines IL-4, IL-13, and IL-5, to activate the M2 macrophage protumor phenotype and increase metastasis potential of breast carcinoma." (PMID 31145753, 2019). "Here, we find that IL-4/IL-13 polarized M2a macrophages enhance breast cancer cell migration and invasion at a greater rate than either M2b or M2c macrophages and are thus an important subpopulation to target therapeutically." (PMID 31214501, 2019). "Pathological changes in tumors and serum expression of interleukin-4 in a mouse model of breast cancer were detected after THSWD treatment." (PMID 32038266, 2019). "In this study, our data defines IL-4/IL-13 stimulated macrophages (M2a macrophages) as the strongest inducers of breast cancer cell migration and invasion." (PMID 31214501, 2019). "In this study, the expressions of TNFα, NF-κB p50 subunit, and IL-4 were related to specific clinicopathologic characteristics in breast cancer." (PMID 29315254, 2018). "We then compared the phenotype and function of 1G (signal 1 only), 1G.4/7ICR (signals 1 + 3), 2G (signal 1 + 2), and 2G.4/7ICR (signals 1 + 2 + 3) T cells when co-cultured with MDA MB 468 breast cancer cells in the presence of IL4 (400 U/mL)." (PMID 29747685, 2018). "The implication of IL-4 in the pathogenesis of breast cancer development and resistance to apoptosis and local metastasis is reported in several studies." (PMID 30648081, 2018). "In this line, the recombinant VSV expressing IL-4 (rVSV-IL4) exhibited considerably higher oncolytic activity against breast cancer or melanoma tumors in murine models." (PMID 29473868, 2018). "Blockade of the macrophage chemoattractant CSF-1 and repolarization of macrophages into a M1 tumor suppressive phenotype by blocking interleukin-4 (IL-4) and IL-13 significantly improved responses to radiotherapy in a mouse breast cancer model." (PMID 30692993, 2018). "The IL-4 receptor is significantly expressed in breast cancer while IL4R is compulsory for the actions of IL-4 on cancer cells." (PMID 30648081, 2018). "Nagai and Toi reported that IL-4 is responsible for the regulation of the enzymes involved in the synthesis of estrogen-promoting apoptosis in cultured breast cancer cells." (PMID 30648081, 2018). "In breast cancer, IL4 is a dominant component of the tumor microenvironment produced both by malignant cells and surrounding adipose tissue." (PMID 29747685, 2018). "Consistent with the RNA expression, protein secretion from the metformin-treated breast cancer cells also showed decreased expressions of IL-4, IL-10 and IL-13 in the medium and an increased expression of IFN-γ." (PMID 28157701, 2017). "The addition of Compound C to metformin-treated breast cancer cells significantly increased the expressions of IL-4, IL-10 and IL-13 when compared to metformin treatment alone." (PMID 28157701, 2017). "In breast cancer, both autocrine and paracrine IL-4 production regulates BCSCs (breast cancer stem cells) features, including cell proliferation, motility and cytoskeletal organization via the RAS/MAPK pathway." (PMID 28927416, 2017). "MiR-223, a miRNA transported from exosomes released from IL-4-activated macrophages to breast cancer cells, promote breast cancer cell invasion via modulation of the β-catenin pathway." (PMID 28974015, 2017). "Further research supported the important role of IL-4 in the expression of breast cancer related hormones, specifically estrogen." (PMID 28927416, 2017). "STAT6 is induced by and required for IL-4-mediated growth inhibition and induction of apoptosis in human breast cancer cells, confirming its anti-tumor function in BC." (PMID 28422733, 2017). "In support of this, systemic neutralization of IL-4 using a monoclonal antibody in a murine spontaneous mammary cancer model was shown to reduce tumor lung metastasis." (PMID 28927416, 2017).
breast carcinoma (continued). "Our previous results show that morphine decreases the alternate activation/M2 polarization of cultured macrophage cells exposed to either IL-4, the prototypical alternate activation-inducing cytokine, or to paracrine stimulation by breast cancer cells." (PMID 27514308, 2016). "IL-4 down-regulated the surface expression of IL-4Rα on one human renal cancer cells, gastric cancer cells and breast cancer cells, and thus showed much higher cell growth-inhibitory effects of IL-4 than IL-4R non expressed cells." (PMID 26993600, 2016). "Regarding anti-inflammatory interleukins, our study sustains a protector action of the anti-inflammatory cytokines IL-4 and IL-10 in female dogs' mammary tumors." (PMID 26989335, 2016). "The ability of morphine to reduce arginase-1 expression in IL-4- or 4T1 breast cancer cell-activated macrophages is likely to be beneficial in the context of tumours." (PMID 26078009, 2015). "A mouse tumor model of mammary carcinomas demonstrated that IL-4-expressing CD4+ T cells indirectly promote the invasion and metastasis of mammary adenocarcinomas by promoting the protumor function of TAMs." (PMID 26242181, 2015). "IL-4-expressing Th2 lymphocytes regulate the phenotype and behaviour of TAMs in vivo, resulting in increased breast cancer metastasis." (PMID 26078009, 2015). "When coculturing with breast cancer cells, IL-4-activated macrophage transported microRNAs from itself to breast cancer cells, and one of microRNAs, miR-223, promoted the invasion of breast cancer cells via the Mef2c-β-catenin pathway." (PMID 26161392, 2015). "GFP-expressing AC2M2 mouse mammary carcinoma cells were transduced with empty vector control (EV-) or mouse IL-4 expressing (IL4-) retroviruses." (PMID 27563494, 2015). "IL-4, a Th2 cytokine, has been showed increased in the microenvironment of breast carcinomas, and IL-4R was overexpressed by breast cancer cells themselves." (PMID 26313265, 2015). "To determine the effect of CCL18 on miRNA expression in breast cancer cells, we performed miRNA microarray analysis for MDA-MB-231 breast cancer cell line 24 hr after exposure to CCL18 or co-cultured with IL-4 stimulated M2 macrophages." (PMID 26244871, 2015). "In the present study, we employed two separate models of in vitro activation of macrophages, namely IL-4 exposure and paracrine activation by breast cancer cells." (PMID 26078009, 2015). "Up to now, the association of IL-4 VNTR polymorphism with several diseases such as leiomyoma, cervical cancer, breast cancer, end-stage renal disease, SLE oral cancer, and Kawasaki disease has been investigated." (PMID 24877103, 2014). "In co-culture experiments, tumor-associated macrophages were shown to transfer miR-223, a microRNA specific for IL-4 activated macrophages, into breast cancer cells, where it promoted invasion through activation of the Mef2c-β-catenin pathway." (PMID 23839094, 2013). "In another study, The effects of human IL-4 and IL-13 on clonal growth of breast cancer cells were investigated that revealed IL-13 can reduced clonal growth of 3 cell type." (PMID 23108822, 2012). "IL-4 also plays a role in the immune response against various tumors, including breast cancer, by inhibiting tumor angiogenesis." (PMID 22827934, 2012). "In parallel, Cy3-labeled miR-223 from IL-4-activated macrophages was more efficiently transported into SKBR3 breast cancer cells (13.36 ± 3.52%) than the labeled miR-223 from unactivated macrophages (7.85 ± 2.84%)." (PMID 21939504, 2011). "The invasiveness of the co-cultivated breast cancer cells decreased when the IL-4-activated macrophages were treated with a miR-223 antisense oligonucleotide (ASO) that would inhibit miR-223 expression." (PMID 21939504, 2011).
breast carcinoma (continued). "We utilized a co-culture system with IL-4-activated macrophages and breast cancer cells to verify that miRNAs are transported from macrophages to breast cancer cells." (PMID 21939504, 2011). "In our studies, IL-4-activated macrophages efficiently secrete and deliver miR-223 to breast cancer cells, and miR-223 is responsible for macrophage-promoting breast cancer cell invasion." (PMID 21939504, 2011). "Co-culturing with IL-4-activated macrophages reduced luciferase reporter activity in SKBR3 breast cancer cells, which suggests that the elevated miR-223 levels observed in breast cancer cells are capable of silencing target gene expression." (PMID 21939504, 2011). "Consistent with previous studies, co-culture with IL-4-activated macrophages enhanced breast cancer cell invasion relative to control cells cultured alone or to co-culture with unactivated macrophages." (PMID 21939504, 2011). "Exosomes secreted from IL-4-activated macrophages shuttle miR-223 into breast cancer cells, and miR-223 promotes breast cancer cell invasion." (PMID 21939504, 2011). "In a mouse mammary tumor model, IL-4-expressing CD4+ T cells induced TAMs with the M2 phenotype to enhance tumor invasion and metastasis." (PMID 24213108, 2011). "Dipterinyl calcium pentahydrate (DCP) has previously been shown to inhibit MDA-MB-231 human breast cancer xenographs in nude mice in a manner correlated with increases in plasma IL-12 and IL-4 concentrations, and decreases in plasma IL-6 levels." (PMID 20356392, 2010). "The cytokines of the IL-1 family, IL-4 and its receptor, IL-6 and IL-10 are important candidate genes as they play an important role in breast cancer pathogenesis." (PMID 16842617, 2006). "IL4 receptor is significantly expressed in breast cancer and it has been shown that IL4R is required for actions of IL4 on breast cancer cells including the inhibition of growth and induction of apoptosis." (PMID 16842617, 2006). "IL-4 inhibits tumour growth by its anti-angiogenic effect and inhibits growth and induces apoptosis of breast cancer cell lines in the presence of IL-4R." (PMID 16842617, 2006). "Using the classic procedure of blood monocyte derived DC culture (in the presence of IL-4 and GM-CSF), the ex vivo yield of DCs was found to be significantly reduced in patients with cancer, particularly in those with breast cancer." (PMID 15987427, 2005). "Additionally, we have previously shown that IL4 increases expression of the glucose transporter GLUT1 in breast cancer cell lines." (PMID 38731867, 2024). "In addition, macrophages polarized by IL4 signaling secrete factors that promote the invasion and migration of breast cancer." (PMID 38731867, 2024). "CD4+ T cells have two subsets—Th 1 and Th 2 cells—and some clinical data observed unbalanced Th 1/Th 2 levels in patients with breast cancer, where Th 2 cells released the cytokines IL-4 and IL-10 and suppressed the host immune system, exhibiting a tumour-promoting effect." (PMID 39624160, 2024). "IL-4 and IL-13, in particular, support breast cancer cell survival, proliferation, and metastasis." (PMID 39456897, 2024). "Imani and colleagues have confirmed that oral administration of Lactobacillus acidophilus, a type of probiotic, can stimulate the generation of IFN-γ while reducing the production of IL-4, thereby enhancing the immune response, inhibiting breast cancer cells, and strengthening the anti-tumor effect." (PMID 39175566, 2024). "Since we observed increased glucose uptake with IL4 treatment, we investigated whether the pAKT/pACLY signaling axis was also affected by IL4 signaling in the context of breast cancer." (PMID 38731867, 2024). "Similarly, Zhao and colleagues also observed higher serum levels of TNF-α, IL-1β, and Interleukin 4 (IL-4) in breast cancer patients after chemotherapy." (PMID 38348396, 2024).